LINC02041 (long independently transcribed non-coding RNA 2041)
Synonyms: RP11-567G11.1
Gene: Long non-coding RNA gene on chromosome 3 (187,448,845 to 187,449,450, forward strand). Ensembl gene ENSG00000228952.
Diseases named in the same sentence as LINC02041 in open-access papers:
LINC02041 is named in the same sentence as 1 disease in open-access papers, as found by Europe PMC text mining. Sharing a sentence is not in itself a finding about the gene and the disease. The quoted sentences say what the papers report.
tumor (1 paper, 2022). "The results showed that AC005332.6, AC090114.2, LINC00857, and LINC02041 were all upregulated in tumor cells, while AL117382.1 was downregulated in tumor cells (p < 0.05)." (PMID 36359832, 2022).